CTSB (cathepsin B)
Diseases named in the same sentence as CTSB in open-access papers (continued):
Sharing a sentence is not in itself a finding about the gene and the disease.
diabetic nephropathy (2 papers, 2023 to 2025). "Similarly, in a diabetic nephropathy model induced by high glucose levels in normal rat kidney-52E cells, CTSB acts as an upstream signal for a decrease in or loss of the mitochondrial membrane potential." (PMID 40129990, 2025). "CTSB has also been mentioned many times as an effective intervention target for kidney diseases, including diabetic nephropathy and hypoxia-induced kidney damage." (PMID 40129990, 2025). "Collectively, our study identifies a novel blood pressure reducing role of metformin in diabetic nephropathy by regulating the cathepsin B-ENaC axis." (PMID 36830842, 2023). "A study of traditional Chinese medicine for the treatment of diabetic nephropathy revealed that ginsenoside Rh2 could ultimately alleviate diabetic nephropathy by inhibiting LMP, reducing the expression of CTSB and cathepsin L, and inhibiting caspase-1-mediated pyroptosis." (PMID 40129990, 2025).
dilated cardiomyopathy (2 papers, 2024 to 2025). Cardiomyopathy which is characterized by dilation and contractile dysfunction of the left and right ventricles. "A recent study revealed a positive association between the circulating levels of CTSB and the severity of left ventricular dysfunction in dilated cardiomyopathy patients." (PMID 39248527, 2024). "Additionally, it has been found that genetic variation in the CTSB promoter may affect the development of dilated cardiomyopathy." (PMID 40950552, 2025). "Moreover, in patients diagnosed with dilated cardiomyopathy, the expression of CTSB showed a negative correlation with the ejection fraction (EF), with those exhibiting elevated CTSB levels also demonstrating heightened myocardial apoptosis." (PMID 39248527, 2024).
follicular carcinoma (2 papers, 2010 to 2011). "In that study, cathepsin B was found to be up-regulated in the neoplastic tissues of follicular adenoma, follicular carcinoma, and papillary carcinoma when compared to non-neoplastic thyroid tissue." (PMID 24281099, 2010). "Unfortunately, cathepsin B could not distinguish between follicular adenoma and follicular carcinoma." (PMID 24281099, 2010).
frontotemporal lobar degeneration (2 papers, 2016 to 2017). "The gene Niemann-Pick disease, type C2 (NPC2) is upregulated in early disease and is connected to cathepsins L and B (CTSL, CTSB) and GLB1 in the lung network." (PMID 28330499, 2017).
fungal infection (2 papers, 2013 to 2025). "Therefore, BMDCs were treated before fungal infection with bafilomycin, which inhibits the vacuolar H+ ATPase or CA-074, which inhibits cathepsin B activity." (PMID 24340123, 2013).
gastric adenocarcinoma (2 papers, 2014 to 2022). "A significant decrease in the processing of the precursor forms of cathepsin B to their lower molecular weight mature forms (31 kDa) was observed in human gastric adenocarcinoma." (PMID 24527069, 2014). "In the present study, the lysosomal protein expression was similar to the patterns observed for LC3-II formation, including the induction of Lamp2 and cathepsin B in patients with low grade differentiated gastric adenocarcinoma." (PMID 24527069, 2014). "In light of the key role of lysosome signaling in autophagy and apoptosis, the alternations in autophagy-lysosome progression were studied next, based on measurements of Lamp2 and cathepsin B levels in human gastric adenocarcinoma." (PMID 24527069, 2014). "Significant elevation of cathepsin B and Lamp2 levels in human gastric adenocarcinoma was found." (PMID 24527069, 2014). "When human gastric adenocarcinomas were dual-labeled with antibodies, formation of LC3 and immunoreactivity against cathepsin B markedly increased compared with normal tissues." (PMID 24527069, 2014). "In the present study, protein analysis of human gastric adenocarcinoma revealed significant upregulation of autophagy regulatory proteins, LC3, cathepsin B and Lamp2." (PMID 24527069, 2014).
inflammatory brain diseases (2 papers, 2023 to 2025). "In the microglia, cathepsin B is associated with the production of interleukin-1β, and this event is considered a major driver of inflammatory brain diseases and brain aging." (PMID 40427636, 2025).
intrauterine growth-restricted (2 papers, 2019 to 2021). "Additionally, urinary N-acetyl-β-d-glucosaminidase and cathepsin B have been reported to be significantly enhanced in premature and intrauterine growth restriction (IUGR) neonates at 30–40 days of corrected age, and significantly and negatively correlated with renal volume and cortical volume." (PMID 30925803, 2019).
Kawasaki disease (2 papers, 2020 to 2022). A rare inflammatory disease characterized by an acute febrile, systemic, self-limiting, medium-vessel vasculitis primarily affecting children. "Studies on Lactobacillus casei-inducing coronary arteritis in a mouse vascular endothelial cell model in Kawasaki disease revealed the release of cathepsin B, which is a lysosomal protease." (PMID 35528818, 2022). "HMGB1 is reported to induce signalling via the RAGE receptor and the HMGB1/RAGE/cathepsin B signalling pathway, which activates NLRP3-dependent coronary endothelial cell pyroptosis and thus plays an important role in the endothelial damage that occurs in Kawasaki disease." (PMID 32795339, 2020).
leprosy (2 papers, 2016 to 2020). Leprosy is a chronic infectious disease affecting primarily the skin and peripheral nervous system. "The SNP rs55894533 located nearby the 5′ of CTSB gene, which were significantly up regulated in the leprosy patients." (PMID 27976721, 2016). "We confirmed all the known leprosy susceptibility loci and identified four novel loci on 3p25.2 (SYN2), 7p14.3 (BBS9), 8p23.1 (CTSB) and 8q24.11 (MED30)." (PMID 27976721, 2016). "At 8p23.1, Cathepsin B(CTSB) were found to be significantly up regulated in the leprosy patients." (PMID 27976721, 2016). "It is also evident that a block in CTSB expression reduced the migration ability of keratinocytes and unobstructed migration of keratinocytes, which could possibly explain the over expression of CTSB in the leprosy lesion." (PMID 27976721, 2016).
lupus nephritis (2 papers, 2023 to 2025). Glomerulonephritis in the context of systemic lupus erythematosus. "Although the specific mechanism of action of CTSB in the glomeruli of patients with lupus nephritis has not been fully elucidated, this finding highlights its potential importance in glomerular function and disease progression." (PMID 40129990, 2025).
meningitis (2 papers, 2015 to 2018). A disorder characterized by acute inflammation of the meninges of the brain and/or spinal cord. "Brain infections are a common TBI complication and cathepsin B levels are greatly increased in meningitis and sepsis animal models." (PMID 26388830, 2015). "Cathepsin B inhibitors also reduced cytokine IL-1β in pain, meningitis, and RA animal models, IL-18 in a pain animal model, and IL-6 in a RA model." (PMID 26388830, 2015).
myeloid tumor (2 papers, 2021 to 2023). "With respect to serine protease and cathepsins, the upregulation of cathepsin B expression has been reported in myeloid tumor cell lines following TGF-β1 treatment, which identified a link between TGF-β1 signaling and the degradation of ECM components." (PMID 33672763, 2021).
pancreatic disease (2 papers, 2022 to 2024). "Whether CTSB plays a key role in these modes of cell death is not clear, especially in the context of pancreatic diseases." (PMID 35872750, 2022).
pancreatic neuroendocrine tumor (2 papers, 2020 to 2021). Pancreatic endocrine tumor, also known as pancreatic neuroendocrine tumor (PNET), describes a group of endocrine tumors originating in the pancreas that are usually indolent and benign, but may have the potential to be malignant. "It was previously found that the absence of CTSB delays the growth and invasion of pancreatic neuroendocrine tumors." (PMID 33708242, 2021).
parvovirus infection (2 papers, 2017 to 2021). "Interestingly, parvovirus infection of GBM cells is followed by cathepsin B upregulation." (PMID 33557101, 2021).
pituitary adenoma (2 papers, 2019). "A bidirectional-inverted relationship between APAF-1 and cathepsin B expressions may result in changes in pituitary adenoma behavior." (PMID 31649621, 2019). "In addition, studies also showed that low levels of APAF-1 were inversely related to invasiveness, and cathepsin B expression was positively related to invasiveness in pituitary adenomas." (PMID 31920968, 2019).
prostate tumor (2 papers, 2011 to 2018). "In this study, we have demonstrated that MTA1 promotes prostate tumor growth and formation of bone metastasis, at least in part, by positively regulating CTSB expression in the primary tumor cells." (PMID 30027683, 2018). "We showed that MTA1 ablation profoundly suppressed the growth of prostate tumors and the ability of tumor cells to colonize the bone by inhibiting their migratory and invasive properties through repression of cathepsin B (CTSB), a cysteine protease that plays a critical role in bone metastasis." (PMID 30027683, 2018). "Marked increase in MTA1 levels, which is an indicator of advanced castrate‐resistant prostate tumors, might be an important factor in endorsing CTSB‐mediated degradation of basement membrane and in the ability of primary prostate tumor cells to undergo E‐cad‐mediated EMT." (PMID 30027683, 2018). "Rao and colleagues have demonstrated that downregulation of cathepsin B and MMP9 more effectively reduces invasion of prostate tumor cells in vitro and tumor growth in vivo than downregulation of either cathepsin B or MMP9." (PMID 22093547, 2011).
pulmonary TB (2 papers, 2021 to 2024). "Genetic models of association SNV rs1692816 of CTSB gene adjusted for sex and age in patients with extrapulmonary tuberculosis (EPTB) and pulmonary tuberculosis (PTB)." (PMID 33868225, 2021).
silicosis (2 papers, 2021 to 2025). Silicosis is a respiratory disease caused by breathing in (inhaling) silica dust. "In this study, we found that the expression level of cathepsin B was significantly reduced in Pla2g7 KO silicosis mice." (PMID 40389600, 2025).
spinal cord injury (2 papers, 2018 to 2023). Penetrating and non-penetrating injuries to the spinal cord resulting from traumatic external forces (e.g., WOUNDS, GUNSHOT; WHIPLASH INJURIES; etc.). "We have recently shown that proteoglycan degrading Cathepsin B is upregulated in sensory and serotonergic neurons by ISP treatment, which markedly improves functional recovery following contusive spinal cord injury." (PMID 30297691, 2018).
tongue cancer (2 papers, 2022). A malignant neoplasm affecting the tongue. "in tongue cancer patients has observed elevated Cathepsin B in serum and tumor tissues associated with high tumor grade." (PMID 35260133, 2022).
acromegaly (1 paper, 2021). Acromegaly is an acquired disorder related to excessive production of growth hormone (GH) and characterized by progressive somatic disfigurement (mainly involving the face and extremities) and systemic manifestations. "It is worth noting that many years ago, our team suggested that the activity of the cathepsin B enzyme, nowadays considered a myokine, may be taken into account as an overall adjuvant marker of the acromegaly complications." (PMID 34795636, 2021).
acute leukemia (1 paper, 2011). A clonal (malignant) hematopoietic disorder with an acute onset, affecting the bone marrow and the peripheral blood. "Additionally, an ionic cyclopalladated compound with a ferrocene ligand {[Pd(C2,N-(S(-) dmpa)(dppf)] Cl}] (termed BPC) induces apoptosis in acute leukemia cells through a novel lysosomal pathway with cathepsin B acting as the death mediator." (PMID 21994769, 2011).
acute monocytic leukaemia (1 paper, 2017). "Similarly, silver wires induced ROS generation, lysosomal rupture, cathepsin B, caspase-1 and IL-1β production in human acute monocytic leukaemia (THP-1) cells." (PMID 28250714, 2017).
anaplastic thyroid carcinoma (1 paper, 2011). "We provide evidence for the notion that HTh74 cells, although representing anaplastic thyroid carcinoma cells, maintain transport competence and directed cathepsin B-eGFP in both versions, active and inactive, to endo-lysosomes." (PMID 21835049, 2011).
Atrophy (1 paper, 2016). Any weakening or degeneration, especially through lack of use. "In addition, it was reported that CtsB/L KO mice show progressive neuronal loss and substantial brain atrophy, similar as NPC1 deficient mice." (PMID 27902765, 2016).
benign renal neoplasm (1 paper, 2022). "mRNA analysis unveiled a significant CTSB and STFA increase in RCC tissues compared to adjacent non-cancerogenic tissues and a higher CtsB expression in malignant tumors than in benign renal neoplasms." (PMID 35563761, 2022).
brain cancer (1 paper, 2016). A primary or metastatic malignant neoplasm affecting the brain. "The Sloane group found that altered lysosomal locations correlated with increased grade of invasive brain cancer, and later showed that cathepsin B released from these more peripheral lysosomes played a role in tumor invasion." (PMID 26784896, 2016).
cardiac arrest (1 paper, 2018). Cessation of breathing and/or cardiac function. "For example, Cathepsin B1 (CtsB1) gene is conserved between Drosophila and human (cathepsin B) and is associated to cardiac arrest." (PMID 30567354, 2018).
cholera (1 paper, 2015). "In addition, the inability of AQ to inhibit cholera and Pseudomonas toxins, which are both ADP-rybosyltransferases, suggests that AQ’s adverse effect on diphtheria toxin, which is also ADP-rybosyltransferase, occurs by inhibition of host cathepsin B only." (PMID 26310922, 2015).
choriocarcinoma (1 paper, 2012). An aggressive malignant tumor arising from trophoblastic cells. "Loss of the 8p23.3p12 region, previously reported in primary choriocarcinoma, harbored (i) the CTSB gene, a cathepsin implicated in invasion and metastasis and (ii) DLC1 and TUSC3, two tumor suppressor genes that are expressed in the placenta, and often deleted in many cancers." (PMID 22253721, 2012).
chronic cholecystitis (1 paper, 2019). "Having established increased activities of both CTSL and CTSB in GBC as compared to control gallbladder with chronic cholecystitis, we then sought to examine the diagnostic potential of these cathepsins in GBC using ROC analysis." (PMID 31824841, 2019). "In the present study, we have demonstrated a significant increase in the serum levels of CTSL and CTSB in GBC patients as compared to their levels in chronic cholecystitis and healthy controls." (PMID 31824841, 2019).
chronic hepatitis B virus infection (1 paper, 2023). Chronic form of hepatitis B infection. "In PBMCs from patients with chronic hepatitis B virus infection, expression of 18 autophagy-modulating genes was downregulated including GABARAPL1, Atg7 and CTSB as well as LC3-II protein levels." (PMID 36994103, 2023).
chronic lung disease (1 paper, 2018). According to the definitions of the American and British Thoracic Societies, including pulmonary functional tests, X-rays, and CT scans for items such as fibrosis, bronchiectasis, bullae, emphysema, nodular or lymphomatous abnormalities. "Previous work in premature infants and animals has suggested CCSP, cathepsin B and desmosine may all play a role in the development of chronic lung disease." (PMID 29310632, 2018). "Cathepsin B concentration was found to be increased in BALF from baboons who subsequently developed BPD, suggesting a role in the development of chronic lung disease." (PMID 29310632, 2018).
CLN6 disease (1 paper, 2021). "Collectively, these findings suggest that CALR and CTSB can be used as effective biomarkers for CLN6 disease, whereas APOE, CTSZ and HEXA might serve as effective biomarkers for multiple NCL subtypes." (PMID 34870700, 2021). "Finally, like conditioned medium collected from neural cells derived from CLN6 disease mice, urine collected from CLN6 disease sheep also contained abnormal amounts of calreticulin (CALR) and CTSB." (PMID 34870700, 2021). "In addition abnormal amounts of CALR and CTSB were detected in conditioned medium collected from cultured cells derived from CLN6 disease mice and in urine from CLN6 disease sheep." (PMID 34870700, 2021).
cystadenoma (1 paper, 2014). A benign or borderline cystic epithelial neoplasm arising from the glandular epithelium. "Cathepsin B, a cysteine protease, and the cysteine protease inhibitor cystatin C were detected in OC cells and their stroma, and were absent in cystadenomas." (PMID 24860785, 2014).
degenerative intervertebral disc disease (1 paper, 2019). "Interleukin 6 and cathepsin B do not represent good biomarkers of degenerative intervertebral disc disease, since the level of such compounds is increased in the plasma of patients with fractures." (PMID 31482941, 2019).
delirium (1 paper, 2024). A disorder characterized by confusion; inattentiveness; disorientation; illusions; hallucinations; agitation; and in some instances autonomic nervous system overactivity. "From the LASSO coefficients, the vascular wall biology targets (i.e., F2, ADAM10, and CTSB) all show positive effects, meaning that patients with higher values of these biomarkers are more likely to have delirium." (PMID 38346717, 2024).
diabetic retinopathy (1 paper, 2025). "CTSB and CTSD are instrumental in the progression of diabetic retinopathy, highlighting their crucial roles in its worsening condition." (PMID 39964999, 2025).
Down syndrome (1 paper, 2023). "In mouse and human cellular preclinical models of Down syndrome, three-copies of CSTB increases CSTB protein abundance but this is not sufficient to modulate cathepsin B activity." (PMID 37580797, 2023).
Duchenne muscular dystrophy (1 paper, 2025). Duchenne muscular dystrophy (DMD) is a neuromuscular disease characterized by rapidly progressive muscle weakness and wasting due to degeneration of skeletal, smooth and cardiac muscle. "CTSB is a myokine that has previously been shown to be upregulated in the muscle of patients with Duchenne muscular dystrophy, mainly localized to areas of macrophage infiltration." (PMID 39949133, 2025).
ectodermal dysplasia-1 (1 paper, 2013). "The lysosomal number, alkalinity, permeability and cathepsin B activity were determined by flow cytometry with ectodermal dysplasia-1, lysosensor and acridine orange staining, and using cathepsin B specific substrate, respectively." (PMID 24047432, 2013).
endometrioid tumor (1 paper, 2021). A benign, borderline, or malignant epithelial tumor of the female reproductive system characterized by the presence of glands and/or cysts lined by neoplastic cells that resemble endometrial cells. "Reduced expression of CDH1 and KRT18 was significantly associated with high-grade tumors and non-endometrioid tumor histology, while increased expression CTSB, CDH2 and ZEB1 could be observed in serous tumors." (PMID 34936030, 2021).
Erythema (1 paper, 2025). Redness of the skin, caused by hyperemia of the capillaries in the lower layers of the skin. "CTSB is considered a candidate gene associated with keratolytic winter erythema, a condition characterized by periodic skin peeling." (PMID 41380997, 2025).
extrahepatic cholestasis (1 paper, 2025). Impairment of the bile flow caused by an obstruction in the portion of the bile duct system located outside of the liver. "In addition, during extrahepatic cholestasis in mice, liver injury, inflammation, and elevation of indices of hepatic fibrogenesis are cathepsin-B-dependent." (PMID 40427636, 2025).
extrapulmonary tuberculosis (1 paper, 2021). A tuberculosis that occurs at body sites other than the lung. "Genetic models of association SNV rs1692816 of CTSB gene adjusted for sex and age in patients with extrapulmonary tuberculosis (EPTB) and healthy control subjects." (PMID 33868225, 2021).